APOE (apolipoprotein E)
Diseases named in the same sentence as APOE in open-access papers (continued):
Sharing a sentence is not in itself a finding about the gene and the disease.
atherosclerosis (continued). "In addition, in ApoE–/– mice treated with the selective NLRP3 inhibitor MCC950 or silencing Nlrp3 by lentivirus, atherosclerosis progression was reduced, confirming NLRP3 inflammasome as a causative factor." (PMID 36082127, 2022). "To determine whether MSC transplantation has beneficial therapeutic effects in atherosclerosis in SLE, we injected MSCs into the tail vein in ApoE−/−Fas−/− mice." (PMID 35850768, 2022). "Further, chronic exposure to another PXR agonistic EDC, BPA increased atherosclerosis in PXR-humanized ApoE−/− mice without altering plasma lipid levels." (PMID 35406689, 2022). "Besides, our previous study demonstrated that Akt-specific inhibitor MK2206, a clinical phase II drug, showed an anti-atherosclerosis activity in vitro and in vivo, and it reduced plasma-CCL2 levels in ApoE−/− mice." (PMID 35990936, 2022). "In atherosclerosis, antisense suppression of SOCS3 in APOE -/- mice exacerbated atheroma development, whereas adenovirus-mediated upregulation of SOCS3 in the same model suppressed plaque development, in association with reduction in STAT1 and STAT3-dependent gene expression." (PMID 36172348, 2022). "In addition to atherosclerosis, the administration of a HFD to ApoE knockout mice induces the development of hyperlipidemia and accelerates the progression of NAFLD pathogenesis." (PMID 35172845, 2022). "In contrast, Yu and co-workers reported that the expression of TSLP in the cardiovascular tissue of ApoE–/– mice was inhibited, and treatment with TSLP could prevent the development of atherosclerosis in these mice." (PMID 35321112, 2022). "The mean reduction of atherosclerosis by P210-PAM immunization in the current study was 42% and 37% in ApoE–/– mice and A2Kb-Tg ApoE–/– mice, respectively, consistent with the mean reduction of atherosclerosis between 25% and 60% reported by investigators using different formulations." (PMID 35536648, 2022). "In apolipoprotein (Apo)E knockout (−/−) mice that develop a disease similar to human atherosclerosis, NOX activator-1 is increased in aortic atherosclerotic lesions, and double ApoE−/−/NOX1−/− mice show reduced O2•− in the heart and atherosclerotic lesions vs. ApoE−/− animals." (PMID 35883899, 2022). "In the CON group of ApoE−/− mice, atherosclerotic plaques in the aortic sinus were all significantly increased after 6 weeks of HCD treatment, whereas GPE treatment inhibited the progression of atherosclerosis." (PMID 36145277, 2022). "We used HFD-fed ApoE–/– mice that had undergone ovariectomy as a comorbidity model of postmenopausal status and atherosclerosis in women on the basis that E2 deprivation by OVX and HFD consumption in ApoE–/– mice induces dyslipidemia and atherosclerosis." (PMID 35865386, 2022). "The importance of immune cell-derived TNF-α is further demonstrated by an elegant experiment, showing that bone marrow transplantation from animals lacking TNF-α is able to reduce atherosclerosis development in ApoE KO mice." (PMID 33770265, 2021). "Deficiency of p38α MAPK in macrophages does not affect the pathogenesis of atherosclerosis in ApoE-/- mice." (PMID 33171330, 2021). "In fact, g-apoA-IV, that induces inflammatory reactions in endothelial cells and atherosclerosis in ApoE−/− mice, up-regulates endothelial NOR-1 expression." (PMID 34768801, 2021).
atherosclerosis (continued). "While the apoE knock-out mouse is an excellent model of atherosclerosis, the lack of apoE is extremely rare in the human population." (PMID 34816004, 2021). "Atherosclerosis severity in the aortic root area of APOE*3-Leiden.CETP mice varied from type “0” (no lesions) to type “V” lesions (advanced and complex lesions)." (PMID 34052976, 2021). "Therefore, we treat apoE−/− mice and THP-1 derived macrophages with MCC950 to explore its effect on atherosclerosis in this study." (PMID 34588488, 2021). "The latest results suggest that gypenosides may regulate mitochondrial-mediated apoptosis in ApoE−/− mice through the PI3K/Akt/Bad pathways, thus inhibiting atherosclerosis." (PMID 33767629, 2021). "Deletion of apoE, the protein involved in receptor clearance of remnant lipoproteins created from VLDL and chylomicrons, is a widely used recipe for creating accelerated atherosclerosis mice." (PMID 34944423, 2021). "In hyperlipidemic female APOE*3-Leiden.CETP mice, exposure to 12-h shift of light-dark cycles for 15 weeks causes a significant increase in atherosclerosis, while male mice do not." (PMID 33445491, 2021). "The current findings based on aortic rings isolated from apoE−/− mice, an experimental model of atherosclerosis, clearly indicate that chronic LOE treatment improved endothelium-dependent vascular relaxation to Ach in WD-fed apoE−/− mice to a degree comparable to losartan." (PMID 34834858, 2021). "Consistent with previous reports, diet-induced atherosclerosis was prevalent in the aortic arch of ApoE-/- mice but not in C57BL/6J controls." (PMID 34305930, 2021). "The secretion of apoE by macrophages occurs through protein kinase A (PKA) and Ca2+-dependent pathways along the microtubule network, and its specific expression can prevent atherosclerosis." (PMID 34336087, 2021). ".c, 4 weeks) induced atherosclerosis and aneurysm in ApoE−/− CCR2−/− and ApoE−/− CCR2+/+ mice." (PMID 34489714, 2021). "Based on our observation of the differences in eADA activity in WT and female ApoE-/-LDL-R-/- mice, we speculate that factors other than estradiol are involved in the development of atherosclerosis." (PMID 32935303, 2021). "Here, we investigated whether Proc-silencing allows APOE*3-Leiden.CETP mice, like Apoeˉ/ˉ mice, to feature thrombosis as final stage of atherosclerosis." (PMID 34052976, 2021). "After 9 months of HFD-feeding, basal plaque accumulation in normolipidemic mice did not exceed 18% in any segment, whereas in ApoE-deleted groups, atherosclerosis covered ≥ 43% of aortic surface area in each segment." (PMID 34366880, 2021). "An independent study reporting that macrophage-specific human apoE3 transgenic expression reduced atherosclerosis in ApoE−/− mice without hypercholesterolemia improvement is consistent with this interpretation." (PMID 34425108, 2021). "In this study, by comparing the aorta and blood of apoE−/− and C57BL/6 mice fed HFD, we identified that lncRNA H19 could serve an essential function in atherosclerosis." (PMID 34820432, 2021). "The aortic sinus lesion area was significantly increased in HCD-fed AceK supplemented ApoE−/− mice, as compared with HCD-fed mice, indicating AceK may accelerate the development of atherosclerosis." (PMID 34836239, 2021). "Here we show that genetic deletion of Siglec-E accelerated atherosclerosis without affecting lipid profile in apoE−/− mice." (PMID 33397354, 2021). "Further testing in ApoE−/− mice confirmed that (P)RR G-ASOs reduced plasma lipid concentrations but not atherosclerosis." (PMID 35004870, 2021).
atherosclerosis (continued). "As TLR2 plays a pathological role in trigging atherosclerosis and vascular calcification, we thus determined whether TLR2 influences 5-MTP production, we analyzed vascular 5-MTP by IHC in ApoE−/−Tlr2−/− double knockout mice." (PMID 34749728, 2021). "The vascular wall of ApoE−/− mice differs from that of WT mice due to the lack of apolipoprotein E gene expression, thereby promoting dyslipidemia, subintimal inflammation and atherosclerosis development." (PMID 34497312, 2021). "During the development of atherosclerosis, apoE may open the mitochondrial permeability transition pore (MPTP) through the interaction of apoE and VDAC1, thereby playing an important role in mitochondrial dysfunction induced by negatively charged LDL." (PMID 34336087, 2021). "Apolipoprotein E-knockout mice with or without a high-fat diet have been used to study atherosclerosis, plaque rupture, coronary artery disease, and cardiac dysfunction." (PMID 34394711, 2021). "The atherosclerosis model was produced by subjecting ApoE-/- male to either normal or Western diet (WD), and the formation of atherosclerotic plaques was determined by Oil Red O staining with quantitative image analysis." (PMID 33976982, 2021). "In this study, we determined that PB2 not only inhibited the development of atherosclerosis but also increased collagen or SMC content and reduced macrophage accumulation and calcification to enhance the stability of plaques in apoE−/− mice." (PMID 34198832, 2021). "Our data demonstrates that atherosclerosis in ApoE-/- mice affected B cell content on the aorta and not in the spleen, whereas serum hypercholesterolemia in ApoE-/- and ApoE-/- Aid-/- mice appeared to systemically activate splenic germinal center B cells." (PMID 34305930, 2021). "Interestingly, BIRC3 may also play a role in the association between periodontitis and atherosclerosis because BIRC3 was down-regulated in aortic tissues after oral polybacterial infection with P. gingivalis, Treponema denticola, Tannerella forsythia, and F. nucleatum in ApoE null mice." (PMID 33435582, 2021). "ApoE knockout mice developed advanced atherosclerosis related to a decreased plasma H2S level and vascular CSE expression/activity, suggesting disturbance of the vascular CSE/H2S pathway plays a role in the pathogenesis of atherosclerosis." (PMID 33562763, 2021). "Because plasma levels of cholesterol in apoE KO rabbits on a normal diet are not high to be atherogenic, there are not spontaneous atherosclerosis, which is different from apoE KO mice." (PMID 33603774, 2021). "Working on the ApoE−/− atherosclerosis mouse model, Gu and co-workers found that non-immune cells also appear in a pro-inflammatory and stem-/progenitor-like state that is typified by the expression of stem cell antigen 1 (SCA1) in SMCs." (PMID 32630148, 2020). "It was demonstrated that NOX2 was not an atherosclerosis inducer in apolipoprotein E knockout (apoE-KO) mice, which are prone to atherosclerosis development." (PMID 32664404, 2020). "In this study, we aimed to investigate the effects of NORAD on endothelial cell injury, endothelial cell senescence and atherosclerosis and the potential molecular mechanisms involved in cultured human umbilical vein endothelial cells (HUVEC) in vitro and in ApoE-knockout mice in vivo." (PMID 32267831, 2020). "In sum, we found that ApoE−/− mice have no circadian abnormalities and thus are an ideal model for studying the effects of light-induced circadian disruption on atherosclerosis." (PMID 32555251, 2020). "Even in the often-used atherosclerosis-prone ApoE−/− (knock-down) mouse model, plaques formed do not rupture." (PMID 32753036, 2020).
atherosclerosis (continued). "Aldosterone was previously reported to induce inflammation in VSMCs, although a recent ApoE knockout model did not confirm a significant role for the smooth muscle cell MR in atherosclerosis." (PMID 31875423, 2020). "To determine whether METTL14 was involved in atherosclerosis, we detected METTL14 expression in atherosclerotic samples from APOE-knockout mice." (PMID 32802173, 2020). "In this current study we did not aim to understand the sex differences in atherosclerosis development in ApoE KO rats and therefore studied only males." (PMID 32943715, 2020). "Knockout mice lacking APOE were developed in 1992, bringing the first mouse genetic model of atherosclerosis into existence." (PMID 33258000, 2020). "However, RS-LPS reduced lesion formation in ApoE−/− diabetic mice, suggesting the potential environmental dependence of TLR4 blockade on atherosclerosis." (PMID 32002588, 2020). "miR-155 expression was quantified in aortae from ApoE−/− mice fed a 1% cholesterol diet supplemented with CLA blend (80:20, cis-9,trans-11:trans-10,cis-12 respectively) which had been previously been shown to induce atherosclerosis regression." (PMID 33391256, 2020). "MAPK signaling has been confirmed to participate in atherosclerosis by regulating the proliferation and migration of VECs, and miR-29b downregulation attenuated atherosclerosis by suppressing the MAPK signaling pathway and inflammation in the aortas of ApoE−/− mice." (PMID 32963706, 2020). "Double knockout of SR-A and CD36 in APO-E-null mice did not reduce aortic root atherosclerosis compared with APOE-null mice; however, the authors did not study SR-A- or CD36-null mice in isolation." (PMID 33182772, 2020). "All three studies were conducted only in male ApoE−/− mice, so again no sex comparisons can be made, and all mitigated atherosclerosis." (PMID 32664664, 2020). "The ApoE(-/-) mice were fed with high-fat diet (HFD) or normal-fat diet (NFD) for 8 weeks; the aorta was separated and stained with oil red O to evaluate the formation of atherosclerosis." (PMID 32694928, 2020). "The latest research report further confirms the role of PAR1 in the development of diet-mediated atherosclerosis, as one of the articles believes that PAR1 can promote AS in ApoE−/− mice by inhibiting the efflux of cholesterol in macrophages and smooth muscle cells and the recruitment of leukocytes." (PMID 33371312, 2020). "In general, APOE lipidation is highly reliant on the ATP-binding cassette transporter A1, or ABCA1, which moves lipids into apolipoproteins and is known to protect against atherosclerosis." (PMID 32005122, 2020). "In APOE*3Leiden.CETP mice, icosabutate reduced plasma cholesterol and TAG levels via increased hepatic uptake, upregulated hepatic lipid metabolism and downregulated inflammation pathways, and effectively decreased atherosclerosis development." (PMID 32841505, 2020). "Overexpressing TGF-β in hearts of ApoE−/−mice decreases lesion size, reduces T cell infiltration, and increases collagen production in the plaques, demonstrating the critical role of TGF-β for VSMC matrix production and plaque stability in atherosclerosis." (PMID 33193911, 2020). "A previous publication using an ApoE-/- atherosclerotic animal model showed that SIRT6 mRNA and protein levels were downregulated in atherosclerotic aortas and that SIRT6 has a protective role against the development of atherosclerosis." (PMID 33171439, 2020). "We saw that over time, extended HFD-fed MHO model developed atherosclerosis, although aortic plaque deposition was not significantly different between ApoE-/- and DKO mice at 24 weeks." (PMID 33488632, 2020). "It had been confirmed that lack of ApoE resulted in accumulation in plasma of cholesterol-rich remnants and thus induced atherosclerosis." (PMID 33193911, 2020).
atherosclerosis (continued). "In apoE*3-Leiden mouse restenosis model, TLR7/9 activation significantly led to femoral artery cuff intimal hyperplasia and accelerated atherosclerosis and blockade of TLR7/9 significantly reduced neointima formation, atherosclerosis, and macrophage cytokine production." (PMID 32850883, 2020). "Apolipoprotein E knockout (ApoE‐KO) rabbits have been used for the evaluation of extracranial atherosclerosis, but they have not been evaluated for the presence of ICAD." (PMID 32613180, 2020). "Neutralization of IL-1α and IL-1β by induction of neutralizing antibodies resulted in reduced atherosclerosis in Nrf2+/+ApoE−/− but not in Nrf2−/−ApoE−/− mice." (PMID 32596261, 2020). "ApoE-knockout mice fed with a high-fat diet (HFD) show features of atherosclerosis with high serum lipid levels and have been considered as an ideal model for studying atherosclerosis." (PMID 32267831, 2020). "One limitation of the ApoE*3-Leiden model is similar to the other mouse models of atherosclerosis in that thrombosis does not occur." (PMID 33258000, 2020). "For this reason, HFD-fed ApoE−/− mice undergoing abdominal aortic injury, which triggers persistent aortic inflammation, were used to investigate atherosclerosis progression in the BCA." (PMID 32673527, 2020). "Recently, we demonstrated in ApoE ko mice that ATD feeding significantly induced LMP7 expression in plaque macrophages, and that genetic and pharmaceutical inhibition of LMP7 attenuated diet-induced atherosclerosis." (PMID 33195259, 2020). "The levels of total cholesterol, triglycerides, LDL, apolipoprotein A, apolipoprotein B, apolipoprotein E, lipoprotein A, total cholesterol/HDL, and LDL/HDL were all significantly different between patients with atherosclerosis etiology as compared to that with lacunar etiology." (PMID 33050269, 2020). "In apoE-/- mice, overexpression of both SOD1 and catalase, which can degrade hydrogen peroxide, reduced atherosclerosis, while overexpression of SOD1 alone, on the contrary, could enhance the pathology development." (PMID 32245238, 2020). "Nrf2-/ApoE- mice showed attenuation of atherosclerosis without change in lipid metabolism or foam cell transformation when compared to Nrf2+/ApoE− mice." (PMID 32596261, 2020). "ApoE−/− mice globally lacking Dgat1 activity are protected from atherosclerosis by at least two mechanisms: (i) reduced macrophage foam cell formation and increased cholesterol efflux, and (ii) reduced uptake of dietary cholesterol." (PMID 32882484, 2020). "To investigate the potential involvement of BRCA2 in the atherogenic process in an atherosclerosis animal model, we evaluated the expression level of BRCA2 in the aorta of the high‐fat diet fed ApoE‐/‐ (ApoEnull) mice and compared it with the expression of BRCA2 in normal diet fed ApoE‐/‐ mice." (PMID 32638521, 2020). "The ApoE−/− mice were given Ad-NORAD or control Ad-EGFP injection after 8 weeks of HFD, and HFD was maintained for another 8 weeks to study the effect of NORAD knockdown on atherosclerosis development." (PMID 32267831, 2020). "Similar results were reported in an ApoE(−/−) mouse model of atherosclerosis, indicating that GDF15 may play an anti-inflammatory role in the process of atherosclerosis." (PMID 32222153, 2020). "Male (t-test p = 0.001), but not female (Mann-Whitney p = 0.08) ApoE−/− mice housed in constant light had more atherosclerosis in the en face aorta compared to those in control 12 L:12D." (PMID 32555251, 2020). "In this study, atherosclerosis pathway analysis showed that VSMCs, lymphocytes, endothelial cells, monolayer cells, macrophage, and foam cells are critical players in the atherosclerosis pathway induced by TCDD and Aroclor1254 coexposure in ApoE−/− mice." (PMID 32855961, 2020).